SUPT5H (SPT5 homolog, DSIF elongation factor subunit)
Description:
Component of the DRB sensitivity-inducing factor complex (DSIF complex), which regulates mRNA processing and transcription elongation by RNA polymerase II. DSIF positively regulates mRNA capping by stimulating the mRNA guanylyltransferase activity of RNGTT/CAP1A. DSIF also acts cooperatively with the negative elongation factor complex (NELF complex) to enhance transcriptional pausing at sites proximal to the promoter. Transcriptional pausing may facilitate the assembly of an elongation competent RNA polymerase II complex. DSIF and NELF promote pausing by inhibition of the transcription elongation factor TFIIS/S-II. TFIIS/S-II binds to RNA polymerase II at transcription pause sites and stimulates the weak intrinsic nuclease activity of the enzyme. Cleavage of blocked transcripts by RNA polymerase II promotes the resumption of transcription from the new 3' terminus and may allow repeated attempts at transcription through natural pause sites. Following phosphorylation by CDK9, DSIF can also positively regulate transcriptional elongation. Required for the efficient activation of transcriptional elongation by the HIV-1 nuclear transcriptional activator, Tat. DSIF acts to suppress transcriptional pausing in transcripts derived from the HIV-1 LTR and blocks premature release of HIV-1 transcripts at terminator sequences.
Synonyms: SPT5; SPT5H; FLJ34157; Tat-CT1
Tractability: Small molecule: a structure with a bound ligand is known. PROTAC: UniProt records ubiquitination sites on it; ubiquitination databases record sites on it; its protein half-life has been measured.
Gene: Protein-coding gene on chromosome 19 (39,436,156 to 39,476,670, forward strand). Ensembl gene ENSG00000196235.
Subcellular location: Nucleus
Subcellular location (Human Protein Atlas): Nucleoplasm
Pathways (Reactome):
Disease: Abortive elongation of HIV-1 transcript in the absence of Tat; Formation of HIV elongation complex in the absence of HIV Tat; Formation of HIV-1 elongation complex containing HIV-1 Tat; Formation of the HIV-1 Early Elongation Complex; HIV elongation arrest and recovery; Pausing and recovery of HIV elongation; Pausing and recovery of Tat-mediated HIV elongation; RNA Pol II CTD phosphorylation and interaction with CE during HIV infection; Tat-mediated HIV elongation arrest and recovery; Tat-mediated elongation of the HIV-1 transcript
Gene expression (Transcription): Formation of RNA Pol II elongation complex; Formation of the Early Elongation Complex; RNA Pol II CTD phosphorylation and interaction with CE; RNA Polymerase II Pre-transcription Events; RNA Polymerase II Transcription Elongation; RNA polymerase II transcribes snRNA genes
Metabolism of RNA: mRNA Capping
Gene Ontology:
Molecular function: enzyme binding; protein binding; protein heterodimerization activity; RNA binding; RNA polymerase inhibitor activity; mRNA binding; chromatin binding
Biological process: negative regulation of DNA-templated transcription, elongation; negative regulation of transcription by RNA polymerase II; positive regulation of DNA-templated transcription, elongation; positive regulation of macroautophagy; positive regulation of transcription by RNA polymerase II; positive regulation of transcription elongation by RNA polymerase II; transcription elongation by RNA polymerase II; transcription pausing by RNA polymerase II; DNA-templated transcription elongation; regulation of DNA-templated transcription elongation; regulation of transcription by RNA polymerase II
Cellular component: DSIF complex; nucleoplasm; nucleus
Genetic constraint (gnomAD): Loss-of-function variants: 24 observed, 143.42 expected, observed/expected ratio (o/e) 0.17, 90% interval 0.12 to 0.23. The upper end of that interval is the gene's LOEUF score, 0.23, which puts it in group 1 of 6, group 1 being the genes least tolerant of losing a copy. Missense variants: 893 observed, 1,512 expected, observed/expected ratio (o/e) 0.59, 90% interval 0.56 to 0.62. Synonymous variants: 546 observed, 571 expected, observed/expected ratio (o/e) 0.96, 90% interval 0.89 to 1.03.
Homologues: Orthologues: macaque SUPT5H (99% identical), dog SUPT5H (99% identical), pig SUPT5H (99% identical), guinea pig SUPT5H (99% identical), rabbit SUPT5H (98% identical), chimpanzee SUPT5H (98% identical), mouse Supt5 (97% identical), rat Supt5h (97% identical), tropical clawed frog supt5h (91% identical), zebrafish supt5h (88% identical), Drosophila melanogaster Spt5 (55% identical), Caenorhabditis elegans spt-5 (42% identical).
Diseases named in the same sentence as SUPT5H in open-access papers:
SUPT5H is named in the same sentence as 23 diseases in open-access papers, as found by Europe PMC text mining. Sharing a sentence is not in itself a finding about the gene and the disease. The quoted sentences say what the papers report.
breast carcinoma (4 papers, 2008 to 2022). "SUPT5H plays an important role in BRCA tumorigenicity by regulating the expression levels of genes that control the proliferation, migration, cell cycle, and apoptosis of breast cancer MDA-MB-231 cells." (PMID 38091511, 2022).
beta thalassemia (2 papers, 2021 to 2024). Beta-thalassemia (BT) is characterized by deficiency (Beta+) or absence (Beta0) of synthesis of the beta globin chains of hemoglobin (Hb). "As almost the entire spectrum of SUPT5H variants in individuals expressing an unlinked beta-thalassemia phenotype from different geographic areas lead to an LoF, this suggests that an intact C-terminus is essential for the correct function of the Spt5 protein." (PMID 39201615, 2024). "In the first report describing SUPT5H as a gene associated with a beta-thalassemia trait, eight different variants were observed." (PMID 39201615, 2024). "How do carriers of SUPT5H variants compare to carriers of known beta-thalassemia variants at the hematological level?" (PMID 39201615, 2024). "Carriers of SUPT5H LoF variants express a mild beta-thalassemia trait, while double heterozygotes for SUPT5H and a beta-thalassemia variant present with a mild beta-thalassemia intermedia phenotype." (PMID 39201615, 2024). "Considering that carriers of SUPT5H variants have a hematological phenotype comparable to that of beta-thalassemia carriers, the expected phenotypic expression of double heterozygotes is more severe, which seems to be confirmed by the hematologic data." (PMID 39201615, 2024). "LoF variants in SUPT5H are associated with a beta-thalassemia-like phenotype in so-called unlinked beta-thalassemia cases with typically elevated HbA2 and, in most cases, microcytic hypochromic erythrocyte parameters." (PMID 39201615, 2024). "Three individuals from two independent Greek families expressing a non-transfusion-dependent beta-thalassemia intermedia phenotype were characterized to have co-inherited a known Mediterranean beta-thalassemia variant and an additional variant in SUPT5H." (PMID 39201615, 2024). "The comparison of red cell indices amongst different groups of reference samples, beta-thalassemia carriers and carriers of SUPT5H variants and compound heterozygotes provided more insight into the clinical phenotype of reduced SUPT5H expression." (PMID 39201615, 2024). "Here, we give an overview of the literature concerning a recently described association in carriers of SUPT5H Loss-of-Function variants with a beta-thalassemia-like phenotype including the characteristic elevated levels of HbA2." (PMID 39201615, 2024). "As there are only three reported cases of combined beta-thalassemia and SUPT5H LoF variants, it is difficult to determine if this is due to the specific feature of the beta-thalassemia variant or the effect of the interaction of the two variant alleles." (PMID 39201615, 2024). "In beta-thalassemia carriers expressing a more severe clinical phenotype than expected from beta-thalassemia traits, such elevated HbA2 percentages might be an indication for a co-inherited SUPT5H variant." (PMID 39201615, 2024). "That SUPT5H acts as modifier in beta-thalassemia carriers became evident from three reported cases in whom combined heterozygosity of SUPT5H and HBB gene variants was observed to resemble a mild beta-thalassemia intermedia phenotype." (PMID 39201615, 2024). "Even though the number of double heterozygotes is not enough to calculate reliable statistical differences, these findings suggest that there is a modifying effect induced by SUPT5H haplo-insufficiency that down-regulates the beta-globin gene expression in beta-thalassemia heterozygotes." (PMID 39201615, 2024). "SUPT5H is a modifying factor which may play a role in beta-thalassemia carriers who express a more severe phenotype than is seen in simple beta-thalassemia heterozygotes." (PMID 39201615, 2024). "As the modifying effect of SUPT5H LoF is relatively subtle, it might be underdiagnosed amongst beta-thalassemia carriers with a more severe clinical expression." (PMID 39201615, 2024). "The elevated levels of HbA2 in the absence of a beta-thalassemia trait causing variants in the HBB gene is one of the most suggestive elements to identify variants in the SUPT5H gene." (PMID 39201615, 2024).
beta thalassemia (continued). "The identification of LoF mutations in SUPT5H in patients with a beta-thalassemia trait-like phenotype in the absence of HBB mutations created a unique opportunity to study RNA Pol II pausing." (PMID 39201615, 2024). "Additional LoF variants in SUPT5H were found in several other individuals of Dutch, French and Italian ancestry, all of whom presented hematological characteristics consistent with beta-thalassemia traits but were negative for variants in the HBB genes." (PMID 39201615, 2024). "A total of eight different pathogenic variants in the SUPT5H gene have been identified in 25 patients with a similar beta-thalassemia minor phenotype showing no abnormalities in the HBB gene (16, Dutch; 2, French; and 7, Greek)." (PMID 34385932, 2021). "In the example of SUPT5H, NGS has allowed the identification of a new trans-acting factor gene involved in regulating beta-globin gene expression, which results in beta-thalassemia trait when haploinsufficient." (PMID 34385932, 2021).
intrahepatic cholangiocarcinoma (2 papers, 2021 to 2025). A carcinoma that arises from the intrahepatic bile duct epithelium in any site of the intrahepatic biliary tree. "Furthermore, the PIWIL4/SUPT5H complex has been identified as a promising prognostic biomarker for predicting clinical outcomes and immune microenvironment features in intrahepatic cholangiocarcinoma." (PMID 41208974, 2025).
thalassemia (2 papers, 2024 to 2025). An inherited blood disorder characterized by a decreased synthesis of one of the polypeptide chains that form hemoglobin. "Indeed, the effect sizes of SUPT5H LoFs on MCH are among the largest of all genes, and LoFs in this gene can cause a thalassemia phenotype." (PMID 39896538, 2025).
colorectal cancer (1 paper, 2015). A primary or metastatic malignant neoplasm that affects the colon or rectum. "SUPT5H was expressed at a much higher level in the nucleus and cytoplasm of colorectal cancer tissues than in normal colon mucosa tissues." (PMID 26418880, 2015). "Real-time RT-PCR was used to compare the expression level of SUPT5H and hTERT mRNA between colorectal cancer tissues and case-matched normal colorectal tissues of 150 primary colorectal cancer patients." (PMID 26418880, 2015). "We further investigated SUPT5H protein expression in 10 cases of normal colon mucosa tissues and 100 cases of colorectal cancer tissues by immunohistochemistry." (PMID 26418880, 2015). "Significant up-regulation of SUPT5H expression was observed in human colorectal cancer tissues, and inhibition of SUPT5H expression imparted an anti-tumor effect on colon cancer cells." (PMID 26418880, 2015). "The present study determined that SUPT5H expression was apparently up-regulated in human colorectal cancer cell lines and primary cancer tissues." (PMID 26418880, 2015). "SUPT5H mRNA expression was positively correlated with hTERT mRNA expression, and SUPT5H protein expression was correlated with frequent distant metastasis in colorectal cancer patients." (PMID 26418880, 2015). "SUPT5H may potentially serve as a biomarker for oncogenesis and development of human colorectal cancer." (PMID 26418880, 2015). "We verified the tumor-specific binding activity of SPT5 to the hTERT promoter in vitro and in vivo and detected high expression levels of SUPT5H in colorectal cancer cell lines and primary human colorectal cancer tissues." (PMID 26418880, 2015). "SUPT5H was more highly expressed in colorectal cancer cases with distant metastasis than in cases without distant metastasis." (PMID 26418880, 2015). "Although no report has described SUPT5H overexpression in colorectal cancer and other types of cancer, a previous study has demonstrated that SUPT5H is essential for the growth and proliferation of HeLa cells, and SUPT5H knockdown causes senescence." (PMID 26418880, 2015).
COVID-19 (1 paper, 2023). A disease caused by infection with severe acute respiratory syndrome coronavirus 2. "Among these TFs-genes, HDGF, SUPT5H and MLLT1 with 4 edges was considered as key TF-genes which was highly related with regulation of T cell differentiation in elderly COVID-19 patients." (PMID 36966292, 2023). "The TFs-genes network showed that HDGF, SUPT5H and MLLT1, with the most edges, played important roles in age-related processes of COVID-19." (PMID 36966292, 2023).
lung carcinoma (1 paper, 2024). "Remarkably, inhibition of SIRT7 also enhanced the repression of ARF target genes in ARF-positive Calu-3 lung cancer cells further supporting the hypothesis that SIRT7 controls expression of Nectin2, XRCC1, and SUPT5H in an ARF-dependent manner." (PMID 38870055, 2024).
pancreatic carcinoma (1 paper, 2019). "It is noteworthy that amplification of the SUPT5H gene (encoding SPT5) is prevalent in uterine, ovarian, and pancreatic carcinoma (>10% of cases)." (PMID 30928206, 2019).
ulcerative colitis (1 paper, 2025). An inflammatory bowel disease involving the mucosal surface of the large intestine and rectum. "In this study, we identified FOXC1, GABPA, GATA2, and SUPT5H as key transcription factors implicated in the development of ulcerative colitis (UC) through the regulation of gene expression involved in inflammation, immune response, and epithelial barrier integrity." (PMID 41300749, 2025).
uterine carcinoma (1 paper, 2019). A carcinoma involving a uterus. "Our analysis of gene expression profiles of uterine carcinomas with SUPT5H amplifications suggested that these amplifications enable such tumors to escape MYC-dependent transcriptional repression." (PMID 30928206, 2019). "Intriguingly, this gene signature was also repressed in the majority of aggressive sub-entities of uterine carcinoma but not in tumors with amplification of the SUPT5H gene, which encodes SPT5." (PMID 30928206, 2019).
cancer (5 papers, 2015 to 2024). A tumor composed of atypical neoplastic, often pleomorphic cells that invade other tissues. "The results showed that SUPT5H and hTERT mRNA expression levels in cancer tissues were both significantly higher than those in case-matched normal colorectal tissues (p < 0.05)." (PMID 26418880, 2015). "Our results demonstrated that SPT5 contributes to the up-regulation of hTERT expression and tumor development, and SUPT5H may potentially be used as a novel tumor biomarker and/or cancer therapeutic target." (PMID 26418880, 2015). "In addition, inhibition of SUPT5H expression not only effectively repressed telomerase activity, accelerated telomere shortening, and promoted cell senescence in colon cancer cells, but also suppressed cancer cell growth and migration." (PMID 26418880, 2015). "Further studies on the function of SUPT5H and transcriptional regulation of hTERT could lead to a better understanding of the complex regulation of human telomerase in normal and cancer cells, as well as identify new strategies for anti-cancer therapy." (PMID 26418880, 2015). "Most of these genes were cell cycle-related genes, including CHEK1, CDK1, RUVBL2, PSMD14, SUPT5H, RBX1, and AURKA, across 28 cancer types." (PMID 38972884, 2024). "Our results demonstrate that SPT5 contributes to the upregulation of hTERT expression and tumor development, and SUPT5H maybe a novel tumor biomarker or a cancer therapeutic target." (PMID 26418880, 2015). "Interestingly, the expression of PIWIL4 (both mRNA and protein) as well as that of a transcription promoter-binding protein SUPT5H, were found significantly upregulated in intrahepatic CCA, and could be potentially used as prognostic markers for this cancer." (PMID 38903178, 2024).
tumor (5 papers, 2019 to 2024). "Univariate and multivariate regression analyses identified two independently survival-related DE-RBPs, namely PIWIL4 and SUPT5H, with the coefficients being less than 0, suggesting that they were key protective factors in tumour progression." (PMID 34876138, 2021). "We investigated the correlation of PIWIL4 and SUPT5H with the tumour microenvironment, and the results suggested that the high riskScore was positively related to the enrichment of resting natural killer (NK) cells and activated memory CD4 + T cells." (PMID 34876138, 2021). "Therefore, we propose that the amplification of SUPT5H enables tumor cells to escape MYC-driven apoptosis." (PMID 30928206, 2019). "Notably, we validated that PIWIL4 and SUPT5H expression pattern in ICC using the laboratory experiments, which indicated that both PIWIL4 and SUPT5H might involve tumour progression of ICC." (PMID 34876138, 2021).
infection (4 papers, 2004 to 2022). The state of being infected such as from the introduction of a foreign agent such as serum, vaccine, antigenic substance or organism. "In contrast, in the JiL cell lines, which were generated by isolating clones from the population of cells that were transcriptionally silenced shortly (4 days) after infection, the sgRNAs targeting SUPT5H and NELFA were enriched to a much lesser extent." (PMID 33270809, 2020).
SUPT5H also shares sentences with these, for which no sentence is quoted: brain tumor (2 papers); amyotrophic lateral sclerosis (1); anemia (1); beta-thalassemia intermedia (1); frontotemporal dementia (1); HIV-1 infection (1); Huntington disease (1); lymphoma (1); neurodegenerative disease (1); spinocerebellar ataxia type 36 (1).